ANGPTL4 (angiopoietin like 4)
Diseases named in the same sentence as ANGPTL4 in open-access papers (continued):
Sharing a sentence is not in itself a finding about the gene and the disease.
osteosarcoma (10 papers, 2015 to 2025). A usually aggressive malignant bone-forming mesenchymal neoplasm, predominantly affecting adolescents and young adults. "Knocking down ANGPTL4 in osteosarcoma cells causes an accumulation of branch chain amino acids, by activating the mTOR signaling pathway and promoting the development of osteosarcoma." (PMID 38586328, 2024). "However, little is known about not only biological functions, but also underlying mechanism of ANGPTL4 in the progression of osteosarcoma (OS)." (PMID 35461343, 2022). "Overexpression of ANGPTL4 promotes proliferation and migration and inhibits cell cycle arrest in thyroid, ovarian and squamous cell carcinoma and osteosarcoma, while suppression of ANGPTL4 reverses this behavior." (PMID 39859313, 2025). "The magnitude of hypoxic induction of ANGPTL4 varied from 3.4- to 35-fold between the different osteosarcoma cell lines." (PMID 29739381, 2018). "76/109 osteosarcomas expressed ANGPTL4, with 51 tumours showing low level expression and 25 high level expression." (PMID 29739381, 2018). "We therefore investigated the expression and function of ANGPTL4 in human osteosarcoma tissue and cell lines." (PMID 29739381, 2018). "In agreement with this literature, MG63 cells over-expressing ANGPTL4 exhibited increased proliferation and migration capacity in comparison with control cells, supporting a stimulatory effect of ANGPTL4 on disease progression in osteosarcoma." (PMID 29739381, 2018). "ANGPTL4 was induced by hypoxia in 6 osteosarcoma cell lines, under the control of the HIF-1α transcription factor." (PMID 29739381, 2018). "Lack of detailed knowledge of the downstream molecular effects of ANGPTL4 and how they are mediated is possibly the major obstruction to furthering our understanding of the role(s) of the individual forms of ANGPTL4 in osteosarcoma and other cancers." (PMID 29739381, 2018). "Investigating the expression and function of ANGPTL4 in osteosarcoma will provide fundamental information as to its suitability as a target for the treatment of osteosarcoma." (PMID 29739381, 2018). "As hypoxia and HIF correlate with the progression and recurrence of osteosarcoma and are predictive of poor survival, increased expression of ANGPTL4 in stage 2 pre-metastatic disease is potentially a mediator of this phenotype." (PMID 29739381, 2018). "Indeed, ANGPTL4 expression correlated with a decrease in cell proliferation in a model of osteosarcoma by limiting aberrant branched-chain amino acid metabolism, which is often linked to cancer progression and invasion." (PMID 36430793, 2022). "Although ANGPTL4 was demonstrated to be the direct target of miR-29b-3p in osteosarcomas, the regulatory mechanism of ANGPTL4 in lipid metabolism of CRC cells remains unclear." (PMID 34680556, 2021). "Similarly, ANGPTL4 is highly expressed in hypoxic-induced osteosarcoma cells and promotes osteosarcoma cell proliferation and migration as well as osteoclast formation and bone resorption activity." (PMID 33203792, 2020). "Expression of ANGPTL4 in osteosarcoma tissue microarrays was determined by immunohistochemistry." (PMID 29739381, 2018). "Here we present the first description of expression of ANGPTL4 in human osteosarcoma tissue." (PMID 29739381, 2018). "We next considered whether ANGPTL4 might enhance the tumourigenic properties of osteosarcoma cells, as seen in other tumour types." (PMID 29739381, 2018). "However, searching publicly available databases indicated increased expression of ANGPTL4 mRNA in grade 2 osteosarcomas versus either low grade tumours or those that had metastasised." (PMID 29739381, 2018). "ANGPTL4 also enhances osteoclast activity, which is required for osteosarcoma growth in bone." (PMID 29739381, 2018). "This suggests that ANGPTL4 over-expression may promote primary osteosarcoma infiltration and extension outside the bone." (PMID 29739381, 2018).
osteosarcoma (continued). "This study describes a role(s) for ANGPTL4 in osteosarcoma and identifies ANGPTL4 as a treatment target that could potentially reduce tumour progression, inhibit angiogenesis, reduce bone destruction and prevent metastatic events." (PMID 29739381, 2018). "Secretory glycoprotein angiopoietin-like 4 (ANGPTL4), a regulator of lipid metabolism, has also been found to participate in the growth and metastasis of osteosarcoma (OS) through activation of the mTOR signaling pathway." (PMID 40625923, 2025). "Exposure to either HIF-1α siRNA, HIF-2α siRNA or HIF-1α plus HIF-2α siRNA suppressed secretion of ANGPTL4 under hypoxia, showing that ANGPTL4 is a target gene of both HIF-1α and HIF-2α in osteosarcoma cells." (PMID 29739381, 2018). "Seven different osteosarcoma cell lines (MG-63, MHM, HOS-143B, IOR-OS18, HOS, ZK-58 and OSA) were assessed for basal secretion of ANGPTL4 which, with the exception of MG-63 and MHM cells, was almost undetectable." (PMID 29739381, 2018). "Reports in other cell lines described ANGPTL4 as regulated solely by HIF-1α, however hypoxic induction of ANGPTL4 was also regulated by both HIF-1α and HIF-2α in osteosarcoma cells." (PMID 29739381, 2018). "Clinical and patient data is not available for the tissues in this TMA; it was therefore not possible to tell whether ANGPTL4 expression levels correlated with clinical characteristics of osteosarcoma." (PMID 29739381, 2018). "Angiopoietin-like 4 (ANGPTL4) drives the progression and metastasis of many solid tumours, but has not been described in osteosarcoma tissue." (PMID 29739381, 2018). "ANGPTL4 expression has not been described in osteosarcoma tissue, although as a HIF target gene it is likely that ANGPTL4 is over-expressed in osteosarcoma and may correlate with features of tumourigenesis or metastasis." (PMID 29739381, 2018). "Indeed, we observed that HIF-1 target genes ANGPTL4, VEGFA, GLUT1, PGK1 and HK2 were down-regulated at mRNA level when DEC2 is knocked down in several osteosarcoma cell lines, while the mRNA level of HIF-1α showed no obvious change by the DEC2 knockdown." (PMID 25884381, 2015).
glioma (9 papers, 2013 to 2025). A benign or malignant brain and spinal cord tumor that arises from glial cells (astrocytes, oligodendrocytes, ependymal cells). "Furthermore, high expression of Sp4 or ANGPTL4 significantly associated with high risk of glioma, and contributed to poor survival in GBM patients." (PMID 31717924, 2019). "ANGPTL4 overexpression can lead to the enrichment of glioma stem-like cells (GSCs), which is distinguished by the level of polycomb complex protein BMI-1 and SOX2." (PMID 36247876, 2022). "Overexpression of ANGPTL4 is capable of inducing the enrichment of GSCs and leads to the resistance of glioma cells to temozolomide." (PMID 36247876, 2022). "A recent study showed that ANGPTL4 induces temozolomide resistance in U87 and Pt#3 GB cell lines by promoting glioma stem-like cells enrichment via the EGFR/AKT/4E-BP1 signaling pathway." (PMID 32867190, 2020). "STAT3 and ANGPTL4 expression was examined in 10 normal brain samples, 466 individual low-grade glioma patients and 328 individual high-grade (GBM) patients." (PMID 25955030, 2015). "MES-like glioma cells expressed multiple receptors for ANGPTL4, including SDC2 SDC3, SDC4, and integrins ITGA5 and ITGB1, suggesting that the ANGPTL pathway may be responsible for the enrichment of GSCs in ECMhi tumors." (PMID 37884531, 2023). "MES-like glioma cells expressed multiple receptors for ANGPTL4, including syndecans SDC2, SDC3, and SDC4 as well as WNT5A receptor FZD6, suggesting that these pathways may be responsible for the enrichment of GSCs in ECMhi tumors." (PMID 37292803, 2023). "Enhanced glioma tumorigenicity upon CBS loss was associated with upregulation of HIF-2α protein level and HIF-2α-dependent transcriptional activation of angiopoietin like 4 (ANGPTL4) and vascular endothelial growth factor A (VEGFA)." (PMID 30050925, 2018). "We then analyzed whether the expression of STAT3 and ANGPTL4 was correlated with glioma grade in the TCGA database." (PMID 25955030, 2015). "High STAT3 and ANGPTL4 levels were observed in high-grade (GBM) samples in the TCGA database when compared to normal brain and low-grade glioma." (PMID 25955030, 2015). "Both STAT3 and ANGPTL4 expression is significantly increased in GBM samples when compared to normal tissue and low-grade gliomas." (PMID 25955030, 2015). "In conclusion, we demonstrated in this study that EGFRvIII induces Angptl4 expression through the ERK/c-Myc pathway, and that Angptl4 is a possible inducer of tumor angiogenesis in gliomas expressing EGFRvIII." (PMID 23617883, 2013). "ANGPTL4 overexpression can induce the GSCs enrichment, which is characterized by the expression of polycomb complex proteins BMI-1 and SOX2, contributing to the resistance of glioma cells to temozolomide." (PMID 36247876, 2022). "The results of the ChIP assay revealed enhanced binding between c-Myc and the promoter region of Angptl4 in LN229-vIII cells, suggesting that the transcriptional regulation of Angptl4 by c-Myc might contribute to the induction of angiogenesis in gliomas." (PMID 23617883, 2013). "Although it has been reported that Angptl4 transcription is regulated by the MAPK signal cascade, the involvement of Angptl4 transcription in EGFR signaling in glioma cells is largely unknown." (PMID 23617883, 2013).
minimal change disease (9 papers, 2014 to 2025). "Initial studies have revealed increased podocyte expression of ANGPTL-4 in minimal change disease (MCD), and it causes increased proteinuria in membranous nephropathy (MN)." (PMID 28978304, 2017). "SAA combined with prednisone exhibited therapeutic and antiproteinuric effects on adriamycin-induced minimal change disease rat model through PPARγ/Angptl4 and Nrf2/Heme oxygenase-1 (HO-1) pathways." (PMID 35528835, 2022). "An experimental study found increased expression of ANGPTL4 to be an early biomarker of podocyte injury in a minimal change disease rat model." (PMID 32269565, 2020). "Increasing evidence has shown that ANGPTL-4 is overexpressed in minimal change nephropathy, which is correlated with proteinuria." (PMID 28978304, 2017). "Angiopoietin-like 4 (ANGPTL4), a multifaceted secreted protein, gained prominence in the field of nephrology when Chugh's team reported a significant increase in both serum and podocytes in human and experimental minimal change disease (MCD) models." (PMID 39776814, 2025). "In the present study, we established an experimental minimal change disease (MCD) rat model, induced by adriamycin (ADR) and resulted in definite podocyte injury, to identify the dynamic changes in Angptl4 expression." (PMID 26352670, 2015). "Recent research showed that podocyte-secreted glomerular Angptl4 was upregulated in experimental minimal change disease (MCD) and MN, and Angptl4 transgenic rats resulted in a high level of proteinuria, indicating that Angptl4 mediates proteinuria in some types of glomerulonephropathy." (PMID 25165975, 2014).
diabetic retinopathy (8 papers, 2018 to 2025). "ANGPTL4 can regulate the angiogenesis mechanism of retinal vascular endothelial cells and delay the progression of diabetic retinopathy." (PMID 40032635, 2025). "Particularly interesting is ANGPTL4, which has been identified as a significant factor in the development and progression of diabetic retinopathy (DR), thus becoming a central focus of DR research." (PMID 40559376, 2025). "In diabetic retinopathy, hypoxia-inducible factor-1 upregulates ANGPTL4 expression in Müller cells of the hypoxic retina, thereby promoting vascular permeability." (PMID 38233877, 2024). "ANGPTL4 plays a key role in the pathogenesis of various retinopathies, including diabetic retinopathy, and several studies have suggested that targeting ANGPTL4, in particular cANGPTL4, may be beneficial in combination with VEGF-targeted therapies." (PMID 40723247, 2025). "Additionally, research has demonstrated that ANGPTL4 may contribute to diabetic retinopathy by increasing vascular permeability through the activation of hypoxia-inducible factor-1 in hypoxic retinal Müller cells." (PMID 40137149, 2025). "ANGPTL-4 induces diabetic retinal inflammation, whereas PLGF is recognized as a homolog of VEGF and a player in diabetic retinopathy." (PMID 35740425, 2022). "Elevated levels of ANGPTL4 in PDR in patients were already reported before and the factor is discussed as potential therapeutic target for patients suffering from diabetic retinopathy." (PMID 29177891, 2018).
gestational diabetes (8 papers, 2013 to 2025). Carbohydrate intolerance first diagnosed during pregnancy. "ANGPTL4 concentrations have been associated with an increased neonatal fat mass in pregnant women with gestational diabetes, and experimental models have been related to maternal blood triglyceride concentrations." (PMID 36768809, 2023). "The expression of ANGPTL3, ANGPTL4, and ANGPTL8 in the placenta of women with gestational diabetes has previously been shown to be positively correlated with birth weight of the offspring." (PMID 39984579, 2025).
heart failure (8 papers, 2016 to 2026). Inability of the heart to pump blood at an adequate rate to meet tissue metabolic requirements. "However, a study of patients recorded in the Chinese PLA Heart Failure Registry found a correlation between elevated levels of ANGPTL4 and increased risk of heart failure." (PMID 40723247, 2025). "Elevated ANGPTL4 expression has been observed in the serum of patients with heart failure with reduced ejection fraction (HFrEF) and COPD and has been shown to be independently correlated with NT-proBNP." (PMID 41602344, 2026). "Patients with high levels of ANGPTL4 showed a lower incidence of recurrent heart failure during follow-up." (PMID 36782020, 2023). "Induction of both ItgaV (integrin alpha v), and Angptl4 are in response to heart dysfunction and heart failure as these proteins play vital roles in myocardial functions." (PMID 27548259, 2016). "Furthermore, we analyzed the correlation between ANGPTL4, heart failure, and the incidence of recurrent heart failure." (PMID 36782020, 2023). "In the rats with heart failure, QL significantly improved these biochemical parameters and metabolomics profiles, significantly increasing the cardioprotective parameter angiopoietin-like 4 and significantly lowering inflammation-related oxylipins and lysophosphatidic acids compared to benazepril." (PMID 29487344, 2018). "Our work generated new insights into distinct and common features of cardiac fibrosis in murine heart failure including the protective potential of Angptl4 and might serve as a valuable resource for the scientific community to identify disease-specific treatment strategies for HFpEF in the future." (PMID 39311911, 2024). "To support our findings, we then analyzed the relationship between ANGPTL4 levels and clinical outcomes in patients with AMI and heart failure." (PMID 36782020, 2023). "Similarly, plasma levels of ANGPTL4 showed a negative correlation with the incidence of recurrent heart failure." (PMID 36782020, 2023).
lymph node metastasis (8 papers, 2015 to 2026). "Increased ANGPTL4 expression was linked to worse tumor grade (OR = 1.51, P = 0.023), stage (OR = 2.42, P < 0.001), lymph node metastasis (OR = 1.76, P = 0.012), vascular invasion (OR = 2.16, P = 0.01), and lymphatic invasion (OR = 2.20, P < 0.001)." (PMID 40233044, 2025). "The high expression of ANGPTL4 in cancer tissues was significantly associated with lymph node metastasis and advanced tumor stage (p = 0.013 and p = 0.031)." (PMID 35392474, 2022). "The high expression of ANGPTL4 was associated with lymph node metastasis and advanced tumor stage (p = 0.013 and p = 0.031, respectively)." (PMID 35392474, 2022). "The results showed that high serum ANGPTL4 level was significantly associated with vascular invasion (p = 0.0004) and lymph node metastasis (p = 0.006)." (PMID 35392474, 2022). "Therefore, serum ANGPTL4 might be a novel prognostic marker with a significant impact on risk of vascular invasion and lymph node metastasis of CCA patients." (PMID 35392474, 2022). "High ANGPTL4 expression correlated with a poor prognosis, poor differentiation, and lymph node metastasis (LNM)." (PMID 41522514, 2026). "Our meta-analysis revealed that there was a significant association between ANGPTL4 and worse TNM stage, T stage, lymphatic invasion, and lymph node metastasis." (PMID 40233044, 2025). "In univariate survival analysis, patients with stage III disease, higher T stage, low ANGPTL4 expression, lymph node metastasis and vascular invasion had shorter OS and DFS times." (PMID 32928141, 2020). "Moreover, ANGPTL4 was identified as an independent marker for predicting lymph node metastasis in both univariate and multivariate analysis (RR = 4.371, p = 0.008 and RR = 3.65, p = 0.039)." (PMID 35392474, 2022). "Additionally, serum ANGPTL4 levels were identified as an independent predictor of lymph node metastasis in univariate and multivariate analyses." (PMID 35392474, 2022). "The ROC analysis showed that ANGPTL4 could be used to predict lymph node metastasis patients with the cutoff 0.5399 AU, sensitivity of 71.4% and specificity of 70.8% (AUC = 0.691, YI = 0.423, p = 0.01)." (PMID 35392474, 2022). "Serum ANGPTL4 levels showed superior predictive efficiency compared with CA 19-9 and CEA for vascular invasion and lymph node metastasis." (PMID 35392474, 2022). "To identify independent predictors of vascular invasion and lymph node metastasis of CCA patients, we conducted univariate regression analysis of the following covariates: gender, age, ALT, AST, ALP, CA 19-9, CEA, and ANGPTL4." (PMID 35392474, 2022). "To determine the predictive values of vascular invasion and lymph node metastasis in CCA patients, we analyzed ANGPTL4 levels and current tumor markers, CA 19-9 and CEA between patient groups by Mann-Whitney U-test and ROC analysis." (PMID 35392474, 2022). "Predictive values of serum ANGPTL4, CA 19-9, and CEA levels for vascular invasion and lymph node metastasis of CCA patients, based on the optimal cutoff derived from ROC analysis and YI calculation." (PMID 35392474, 2022). "SPARC, VCAM1 and ANGPTL4 were found positively correlated with the potentials of lung metastasis, while ITGA1 had a positive relation to lymph node metastasis of enterocoelia." (PMID 26459277, 2015). "Serum ANGPTL4 showed a correlation with vascular invasion and lymph node metastasis but did not correlate with tumor stage." (PMID 35392474, 2022). "Indeed, the protein levels of SPARC, ANGPTL4 and VCAM1 were remarkably correlated with the potentials of lung metastasis, while ITGA1 was positively related to celiac lymph node metastasis (p < 0.01)." (PMID 26459277, 2015). "Moreover, serum ANGPTL4 and CA 19-9 levels were significantly higher in CCA patients with lymph node metastasis than in those without lymph node metastasis (p = 0.008 and p = 0.023)." (PMID 35392474, 2022).
lymph node metastasis (continued). "Moreover, higher level of ANGPTL4 in CCA sera could be used to differentiate CCA with vascular invasion and lymph node metastasis from without these complications." (PMID 35392474, 2022).